IL6 (interleukin 6)
Diseases named in the same sentence as IL6 in open-access papers (continued):
Sharing a sentence is not in itself a finding about the gene and the disease.
tumor (continued). "TNF-α is a cytokine produced by macrophages, with a role in the inflammatory response, cellular immunity, tumor immunity, and other physiological processes, while IL-6 is a pro-inflammatory cytokine that stimulates the immune system to repair damaged cells and promote the host survival." (PMID 33919822, 2021). "Moreover, IL-11 and IL-6 drive the malignant development of tumor cells by the activation of STAT3 as well as by the upregulation of angiogenic and inflammatory factors." (PMID 33917793, 2021). "However, these drugs improved symptoms at the cost of unpredictable side effects, presaging a multifaceted correlation among IL-6, tumor and body immune system." (PMID 33390844, 2021). "Furthermore, several reports have demonstrated that IL-6 is a cytokine with significant predictive ability for HCC patient survival and is associated with tumor size and aggressiveness." (PMID 34948424, 2021). "Consistent with the role of IL6 in modulating the tumor microenvironment of NSCLC, patients with high levels of circulating IL6 also display more immunosuppressive Tregs than patients with low IL6 levels and exhibit poorer response to anti-PD1/PDL1 immune checkpoint blockade." (PMID 34944848, 2021). "Tumor secretion factors induce drug resistance through IL-6 upregulation in HMVECs." (PMID 34226586, 2021). "Also, IL-6 enhanced the metastasis rate in breast cancer through the positive effect on tumor stem cell self-renewal and epithelial-to-mesenchymal transition (EMT) process." (PMID 35155571, 2021). "High levels of pretreatment tumor IL-6R and serum IL-6 expression have been shown to correlate with a higher rate of tumor recurrence and reduced survival of HNSCC patients, which emphasizes the relevance of inhibiting this signaling pathway to mitigate the risk of recurrence in HNSCC." (PMID 34689150, 2021). "Whereas IL-6 has mainly pro-tumor activities, IL-27 may have a dual biological role in different cancers." (PMID 34439164, 2021). "Alternatively, growth factors (e.g., vascular endothelial growth factor (VEGF)) and cytokines (e.g., IL-6 and IL-8) present in the tumor microenvironment may increase vascular permeability and induce fluid accumulation." (PMID 34503128, 2021). "Growth factors, interleukin and extracellular matrix constituents (e.g., TGF-β, IL-6, PDGF, FGF and MMPs) generated by TAMs may cause tumor cells to go through GMT (glial-to-mesenchymal), as well as ease divergent invasions." (PMID 34368156, 2021). "Notably, IL-6 not only has an autocrine role in supporting tumorigenesis in vivo, but also in a paracrine manner recruits vascular endothelial cells to support tumor angiogenesis." (PMID 34771644, 2021). "Considering that both IL‐6 and IL‐27 contribute to tumour progression through JAK/STAT3 signalling pathway, we next elucidated whether CD63 regulated the activation of signal transducer and activator of transcription‐3 (STAT3) by Western blot analysis." (PMID 33277798, 2021). "Importantly, we demonstrate that IL-6 education of MDPs alone enhances the metastatic potential of tumor cells." (PMID 34140316, 2021). "With many anti-tumor drugs targeted IL-6 as well as its downstream receptors, it is reasonable to query that to what degree and in what condition that the effect IL-6 induced by the thermal treatment can win against the one it plays in the pro-tumor activities." (PMID 33390844, 2021). "Moreover, LPSlow-macrophages downregulated the expression of inos in spleen (p = 0.03) and il6 both in spleen (p = 0.005) and the tumor (p = 0.02)." (PMID 34413847, 2021). "Together these findings suggest that metformin might mitigate tumor migration via effects on IL-6 production." (PMID 34829914, 2021). "Moreover, IL-6-induced tumor growth of HCC cells via STAT3 phosphorylation at tyrosine 705 in the presence of sorafenib is reversed with IL-6Rα depletion." (PMID 34948424, 2021). "It has been suggested that IL-6 can be secreted directly by the tumour." (PMID 33715142, 2021).
tumor (continued). "Nuclear factor kappa beta and STAT3 hyperactivation in tumor cells and immune cells in the tumor microenvironment in turn promotes production of several pro-inflammatory cytokines including IL-1β, IL-6, and TNFα, which promote survival and proliferation of tumor cells." (PMID 35048057, 2021). "IL-6 is a cytokine that has been related to tumor metastasis and EMT through STAT3 signaling." (PMID 34503180, 2021). "On the other hand, the release of inflammatory mediators, such IL-1, IL-3 and IL-6 by cancer cells, triggers the differentiation of megakaryocytes into platelets, thus fueling a vicious cycle where platelets and tumor cells continuously stimulate each-other’s growth." (PMID 34367964, 2021). "In addition, IL-6 exerts immunosuppressive effects by inhibiting dendritic cells and lymphocytes, by activating Tregs and in fine by promoting tumor immune escape." (PMID 35096626, 2021). "In OC, IL-6 plays a negative prognostic role and is associated with high MDSCs, and tumor progression." (PMID 34503248, 2021). "Interestingly, the overexpression of the CRYBB2 gene in triple negative breast cancer cells promoted tumor progression by increasing growth, invasiveness, IL6 production, immune cell chemo attraction, and the expression of metastasis-associated genes." (PMID 34071280, 2021). "When monocytes are stimulated by inflammatory factors, such as interferon-gamma and lipopolysaccharide, they activate M1 macrophages, which can secrete inflammatory factors, such as IL-6 and tumor necrosis factor-alpha, and can phagocytize invasive pathogens and tumor cells." (PMID 33737938, 2021). "BBR or antibodies to IL-6 and IL-6R may also inhibit STAT3 activation by regulatory media of tumor-associated fibroblasts." (PMID 34885950, 2021). "IL-6 is expressed at high levels in the tumor microenvironment." (PMID 34277446, 2021). "The stromal-derived SASP component IL-6 could increase the number of myeloid-derived suppressor cells (MDSCs) and enhance the ability of MDSCs to inhibit anti-tumor T-cell responses." (PMID 34458273, 2021). "IL-6 produced by the tumor was amplified distantly via production of IL-6 from adipose and muscle." (PMID 33851955, 2021). "IL-6, secreted by cancer-associated fibroblasts, activates the JAK/STAT3, PI3K/Akt, and Ras pathways, which are the three major pathways in endothelial cells involved in tumor development." (PMID 34441316, 2021). "For instance, positive regulation of production of molecular mediator of immune response, T cell related pathways, regulation of interleukin 6 mediated signaling pathway, immunological synapse formation, and positive regulation of natural killer cell mediated immune response to tumor cell." (PMID 35126346, 2021). "Furthermore, STAT3 activation in tumors can be transmitted to immune cells in the tumor microenvironment through secreting mediators such as IL-6 among many other cytokines and growth factors." (PMID 33491667, 2021). "Moreover, in this tumor type, IL-6 silencing leads to the sensitization of tumor cells to irradiation through the increase of cell death and DNA damage." (PMID 34141616, 2021). "Although irradiation may be effective in eliminating some tumour cells, IL-6-expressing tumour cells were unaffected, and moreover, enhanced the acquisition of a radioresistant phenotype by repressing irradiation-induced DNA damage." (PMID 33803414, 2021). "Accordingly, these four isomiRs might prevent the patients from tumor metastasis by repressing the function of IL-6." (PMID 34589114, 2021). "Moreover, the in vivo synergistic anticancer efficacy was evaluated in NCNLCs in xenograft tumor mice models and results showed that NCNLCs upregulated the IL-10 and IL-6 expression in the serum of tumor-bearing mice and inhibited tumor growth." (PMID 33854437, 2021).
tumor (continued). "It has been shown that ARMH4 can interact with and inhibit the function of mTOR complex 2 kinase activity and function as a tumor suppressor in hematological malignancies, which is driven by interleukin 6 (IL-6)–signal transducer and activator of transcription 3 (STAT3) signaling pathways." (PMID 34660292, 2021). "Similarly, chemotherapy also increases the infiltration of the TAMs in the tumor tissues and the activated TAMs also make promotion on the tumor progression by secreting proinflammatory cytokine such as interleukin-6 (IL-6)." (PMID 34722623, 2021). "Genes of the STAT3 pathway and of the STAT3 activator IL6 are significantly enriched in group PF_EPN_A, suggesting the establishment of a feedforward loop between tumor cells and the inflammatory microenvironment, which can provide additional druggable vulnerabilities by BETi in EPN." (PMID 33668642, 2021). "A positive correlation between IL-6 and the size of the tumor has been previously reported." (PMID 34829862, 2021). "As is the case for IL6, other cytokines might exert a complex range of possibly opposite effects, with evidence of anti- and pro-tumour effects." (PMID 34834425, 2021). "Priming pro-tumor neutrophils with IFNγ and TNFα could convert them to tumor-suppressing cells even in the presence of G-CSF and IL-6 by restoring the PI3K and p38 MAPK signaling pathways." (PMID 34572138, 2021). "However, aberrant IL-6 expression also played an important role in tumorigenesis and cancer progression via promoting tumor cell growth and metastasis." (PMID 34122408, 2021). "We next measured spontaneous production of IL-6 and IL-1β in ex vivo cultured bone marrow and spleen cells to determine whether tumor growth influenced host inflammatory responses." (PMID 33649199, 2021). "In addition, hepcidin expression strongly correlated with BMP6 and IL6 genes, as well as anti-cancer immune cell populations in the tumor microenvironment." (PMID 34277457, 2021). "The gene expression of multiple inflammatory markers in the heart was significantly upregulated in tumor-bearing mice as compared to tumor-free mice, including the pro-inflammatory cytokines IL-1α, IL-1β, IL-6, and TNF- α and the inflammatory chemokines Mcp-1, Cxcl1, and Cxcl10." (PMID 34445729, 2021). "Recently, the IL-6 concentration in serum has been defined as a promising tumor marker for HCC." (PMID 34948424, 2021). "On the other hand, persistently high IL-6 levels after initial control of HIV-associated KS with cancer chemotherapy seems to be important for maintenance of disease remission, possibly through promoting anti-tumor effects." (PMID 34214127, 2021). "Indeed, DOX administration normalized tumor-induced upregulation of IL-6 to a similar level as control tumor-free mice." (PMID 34445729, 2021). "In addition, our clinical data showed that IL-6+ signals in TME were stronger in tumor derived from advanced stage patients than those from early ones." (PMID 34093869, 2021). "More recently, in a gastric adenocarcinoma mouse model, it was demonstrated that gastric tumor cells produced IL-33, which resulted in mast cell activation that led to the production of macrophage-attracting factors CSF-2, CCL3, and IL-6 and subsequent tumor growth." (PMID 34063789, 2021). "SHH could be one such molecule, as it has been demonstrated that SHH secreted by tumor cells acts on osteoblasts, which in turn release IL-6, to promote osteoclast differentiation." (PMID 33731701, 2021). "Our findings brought out that tumor-derived acidosis promotes excessive osteolysis at least in part by inducing an inflammatory phenotype in osteoblasts, and these results strengthen the use of anti-IL-6 or anti-IL-8 strategies to treat osteolysis in BM." (PMID 34124067, 2021).
tumor (continued). "Furthermore, it was proven that increases in the levels of IL-6 and G-CSF are dependent on tumor-derived LIF." (PMID 33557173, 2021). "IL-6 promotes the polarization of macrophages into immunosuppressive M-2 like macrophages and has been demonstrated to recruit T-regulator (Treg) cells, both of which work to inhibit an anti-tumor immune environment." (PMID 34497771, 2021). "VAT activates macrophages leading to the secretion of cytokines such as interleukin-6 and tumor necrosis which may potentiate inflammation and fibrosis of the myocardium." (PMID 34120624, 2021). "delineated that Cdc42 could be rapidly and robustly activated by a pro-inflammatory factor Interleukin-6 (IL-6), thus mediating the IL-6 induced promotion of tumor growth and metastasis." (PMID 33726765, 2021). "In addition, patients in the low-risk group had a higher expression level of cytokines in the tumor tissues, such as IL-2, IL-6, and IL-18, which was consistent with more infiltrating immune cells in the low-risk group." (PMID 34616734, 2021). "Therefore, it is necessary to grasp the critical point between the pro-tumor and anti-tumor effects of IL6 in TME-based therapy, so as to carry out a correct and effective response." (PMID 34790130, 2021). "Indeed, SETI administration exerted a significant effect, decreasing the concentration of accepted immunosuppressive tumor markers for HCC such as IL-6." (PMID 34829862, 2021). "Tumor-associated macrophages, major components of tumor microenvironment associated with cancer metastasis, induce EMT for colorectal cancer migration and circulating tumor cell-mediated metastasis via JAK2/STAT3/miR-506-3p/FoxQ1 axis activated by IL-6." (PMID 34660694, 2021). "Reprogramming of fibroblasts to pro-tumoral CAFs, demonstrated by increased proliferation, migration, secretory activity and expression of certain markers, may occur through a combination of tumor-secreted EVs and soluble factors, such as IL-6." (PMID 34207163, 2021). "Likewise, lung cancer-derived ExVs induced DCs to produce IL-6 which promoted tumor invasion by increasing STAT3-dependent MMP 9 transcription activity in tumor cells." (PMID 33435564, 2021). "Taken together, we speculated that tumor cells release IL-6 to stimulate macrophages to up-regulate MMP12." (PMID 34863141, 2021). "Taken together, it is plausible to speculate that nifuroxazide treatment decreases tumor angiogenesis via the inhibition of the IL-6/Jak2/STAT3 pathway." (PMID 34833950, 2021). "MSA could downregulate EGFR via miR-146a and decrease IL-6 secretion, lead to substantial decrease in tumor angiogenesis to inhibit ESCC cell growth." (PMID 34393797, 2021). "Incubation of dendritic cell (DC) cultures with tumor cell supernatants inhibited the production of IL-12p70 in DCs but not the surface expression of other activation markers which is reversed by treatment with IL-6 antibody." (PMID 34671021, 2021). "Another study confirmed these results by demonstrating an upregulation of lincRNA-p21 in TAMs, whereas knockdown facilitated macrophage polarization to M1 by upregulating TNF-α, IL-6, and iNOS, downregulating IL-10, IL-4, and Arg-1, and reducing tumor-cell proliferation and migration." (PMID 34439281, 2021). "However, in both tumor models, anti-IL-6 treatment dramatically reduced the incidence of lung metastasis only in mice harboring met-high tumors." (PMID 34140316, 2021). "Further, IL-6 induced VEGF production by tumor cells and consequently activated angiogenesis." (PMID 33833265, 2021). "As low skeletal muscle mass is related to lower levels of IL‐6, low muscle mass could inhibit the suppression of tumour progression, worsening the prognosis of cancer patients." (PMID 32478975, 2021).
tumor (continued). "Some studies have shown that serum IL-6 levels are related to the tumour stage and size, metastasis and survival of colon cancer patients, chemotherapy efficacy for advanced pancreatic cancer, neoadjuvant chemoradiotherapy for oesophageal carcinoma and metastasis-related morbidity of breast cancer." (PMID 34078370, 2021). "Second, the level of circulating fibrinogen is increased by interleukin-6 secreted by tumor cells, and fibrinogen has been found to interact with several growth factors to induce tumor seeding and promote the invasion of tumor cells, leading to a poor prognosis." (PMID 33849545, 2021). "Notably, IL-6 can stimulate glycolysis within the tumor microenvironment and a disturbed glucose metabolism can elicit proinflammatory effects." (PMID 33925109, 2021). "IL-6 is also upregulated in the tumor microenvironment, where it activates two signaling pathways: (i) JAK2/STAT-3, which induces EMT (upregulation of E- and N-cadherin, MMP7, and MMP9) and increases the metastatic potential; (ii) PI3K/Akt, which promotes cancer cell survival." (PMID 33670492, 2021). "IL-6 may influence tumor cells through many downstream mediators, leading to support metastasis, survival, and proliferation of cancer cells." (PMID 34439305, 2021). "Indeed, the application of anti-IL-6 and anti-IL-6R tocilizumab reduced hypoxia- or TMZ-induced autophagy and caused significant tumour cell apoptosis." (PMID 33803414, 2021). "A recent report shows that HO-1 is a tumour suppressor gene, which is induced by IL-6." (PMID 34047814, 2021). "Among the variety of cytokines and growth factors secreted by CAFs, a great number of studies highlighted the IL-6 and IL-8 essential role in the maintenance of stem-like features of cancer cells and in the promotion of tumor growth, metastasis formation, and chemoresistance." (PMID 34354950, 2021). "An upregulated level of IL-6 in the TME is strongly associated with cancer cell proliferation, epithelial to mesenchymal transition, chemoresistance, invasion, metastasis survival of tumor cells, and angiogenesis through fueling STAT3 MAPK and Akt signaling." (PMID 35010954, 2021). "Likewise, IL-6 relevant lncRNA profiles have been investigated in inflammatory and tumor diseases including CRNV." (PMID 34712495, 2021). "In addition, they also found IL6 expressing cells around Gal-3BP positive tumor cells in NB tissues, which reveals the close relationship between Gal-3BP expression and IL6 secretion." (PMID 34790130, 2021). "Then, we measured IL-6 and IL-10, which were involved in immune response in tumor cells." (PMID 33959183, 2021). "The identification of autophagy mediated IL-6 secretion was notable in the context of bone metastasis, as IL-6 was shown to be secreted by senescent osteoblasts, serving to promote osteoclast differentiation, resulting in enhanced osteolysis and tumor burden in mouse models." (PMID 34503118, 2021). "Hence, p38α inhibition or down-regulation decreases CRC tumor growth, being relevant for it the decrease in the expression of the pro-inflammatory cytokine IL6." (PMID 33922633, 2021). "The blockage of IL-6 counteracted intratumoral NK cell infiltration and tumor suppression." (PMID 33806053, 2021). "In addition, IL-6 can directly stimulate the proliferation, survival, and invasiveness of tumor cells." (PMID 34445405, 2021). "EE lowered circulating myostatin, IL-6 and slowed down tumour growth." (PMID 35008220, 2021). "IL-6 favors RORγt and is aberrantly activated in many tumor microenvironments." (PMID 34489941, 2021).